SLC67A1-AS (SLC67A1 antisense RNA)
Synonyms: p27-BWR1B; BWR1B; BWSCR1B; ORCTL2S; SLC22A18AS; SLC22A1LS; SLC22A18-AS1
Gene: Long non-coding RNA gene on chromosome 11 (2,887,344 to 2,903,814, reverse strand). Ensembl gene ENSG00000254827.
Genetic constraint (gnomAD): Loss-of-function variants: 8 observed, 9.87 expected, observed/expected ratio (o/e) 0.81, 90% interval 0.47 to 1.45. That is too few expected variants to judge how well the gene tolerates losing a copy. Missense variants: 335 observed, 312.95 expected, observed/expected ratio (o/e) 1.07, 90% interval 0.98 to 1.17. Synonymous variants: 143 observed, 121.3 expected, observed/expected ratio (o/e) 1.18, 90% interval 1.03 to 1.35.
Diseases named in the same sentence as SLC67A1-AS in open-access papers:
SLC67A1-AS is named in the same sentence as 3 diseases in open-access papers, as found by Europe PMC text mining. Sharing a sentence is not in itself a finding about the gene and the disease.
SLC67A1-AS shares sentences with these, for which no sentence is quoted: tumor (2 papers); colon cancer (1); lung carcinoma (1).